COL4A5 (collagen type IV alpha 5 chain)
Diseases named in the same sentence as COL4A5 in open-access papers (continued):
Sharing a sentence is not in itself a finding about the gene and the disease.
Microscopic hematuria (7 papers, 2019 to 2023). Microscopic hematuria detected by dipstick or microscopic examination of the urine. "The proband inherited the COL4A5 variant from the mother, as expected for X-linked inheritance, who only presented with microscopic hematuria, and the LAMA5 variant from the father who had microscopic hematuria and unilateral hypoacusia." (PMID 37761826, 2023). "Other examples of use include women presenting with microhematuria and low-grade proteinuria or young boys with COL4A5 pathogenic variants who present with TBMN." (PMID 36553470, 2022). "Women heterozygous for COL4A5 pathogenic variants also present with microscopic hematuria and run a high risk of kidney failure, with 15% of them developing ESRD by the age of 60 years." (PMID 36553470, 2022). "The clinical feature of either paternal CFB variant or maternal COL4A5 variant is just mild microscopic hematuria." (PMID 34349783, 2021). "COL4A5 mutations are typically associated with microhematuria in the first few years of life, slowly progressing to microalbuminuria below 300 mg, but not with high levels of proteinuria such as the 1300 mg/L observed in the two-year-old boy." (PMID 30691124, 2019). "Recently an association of LAMA5 and COL4A5 variants has been described in four family members presenting with microhematuria and proteinuria and progressive ESRD in the spectrum of ATS." (PMID 30808327, 2019). "The case at hand is familial microscopic hematuria due to heterozygous disease-causing variants in the COL4A3 or COL4A4 gene, or even the COL4A5 gene (in women), responsible for the X-linked form of AS." (PMID 37761826, 2023).
end stage renal disease (6 papers, 2016 to 2025). "The average age at end-stage renal failure was the same for all mutations in COL4A5 (24.4 ±7.8 years), COL4A3 (23.3 ± 9.3) and COL4A4 (25.4 ± 10.3) (COL4A5 and COL4A3, p = 0.45; COL4A5 and COL4A4, p = 0.55; COL4A3 and COL4A4, p = 0.41)." (PMID 27627812, 2016). "Age at end-stage renal failure and severity of mutations with COL4A5, COL4A3 and COL4A4 variants." (PMID 27627812, 2016). "Overall the mean age at onset of end-stage renal failure was not different for individuals with COL4A3 (23.2 + 9.3, years, 95% CI 20.1 to 26.5) or COL4A4 mutations (mean 25.4 ±10.3 years, 95% CI 21.3 to 29.6) compared with COL4A5 mutations (24.4 ± 7.8 years, 95% CI 23.4 to 25.4, n = 237)." (PMID 27627812, 2016).
familial hematuria (6 papers, 2018 to 2025). "Although in our study most of the females had only hematuria, three women A5338, A56511, A5343159 with heterozygous variants p.Gly1170Arg, Val473Glufs*3, p.Gly156Arg in COL4A5 had decline of eGFR < 60 ml/min/1.73 m2." (PMID 35419377, 2022). "This duplication-triplication involved COL4A5 (MIM: 303630) and was found in two affected family members recruited to 100kGP with familial hematuria (Family 25)." (PMID 38776926, 2024).
leiomyoma (6 papers, 2022 to 2025). A well-circumscribed benign smooth muscle neoplasm characterized by the presence of spindle cells with cigar-shaped nuclei, interlacing fascicles, and a whorled pattern. "COL4A5/COL4A6 mutated leiomyomas have also been shown to have significantly elevated prolactin and associated genes in genome-wide association studies (GWAS)." (PMID 38957794, 2024). "The driver mutations critical to leiomyoma development and progression include MED12 (mediator complex subunit 12), HMGA2 (high mobility group AT-hook 2), FH (fumarate hydratase), and COL4A5/6 (collagen type IV, alpha 5, and alpha 6)." (PMID 35641855, 2022). "According to studies conducted by Mehine and colleagues, alterations in the COL4A5/COL4A6 locus arose in multiple uterine leiomyoma samples through chromothripsis, a series of complex chromosomal rearrangements associated with aggressive cancer types and tumors, such as leiomyomas." (PMID 38957794, 2024). "The feature selection resulted in a final model that consisted only of 19 genes, out of which only three, COL4A5, MFAP5, and ITGA9, were overexpressed in leiomyoma, while the rest were overexpressed in leiomyosarcoma)." (PMID 35216305, 2022).
hereditary nephritis (5 papers, 2015 to 2025). A group of inherited conditions characterized initially by hematuria and slowly progressing to renal insufficiency. "The patient was later confirmed with XL-AS (a missense mutation of COL4A5 inherited from his mother) at the age of 11 years by genetic testing (A Panel of hereditary nephritis)." (PMID 32703181, 2020). "The objective of this study was to define the SNP profiles for COL4A5 in patients with hereditary nephritis and hematuria." (PMID 26168235, 2015).
IgA nephropathy (5 papers, 2022 to 2024). "The presented case demonstrates a familial COL4A5 novel pathogenic variant (NM_000495.5: c.1095dup) in association with AS in the hemizygous proband as well as with IgA glomerulonephritis and FSGS in the heterozygous mother." (PMID 38790225, 2024). "Renal biopsies were initially inconclusive; however, genetic testing showed that the two individuals diagnosed at different points with IgA nephropathy carried novel segregating pathogenic variants in COL4A5 gene." (PMID 35295700, 2022). "It is unclear whether severe variants predispose more often to kidney cysts or coincidental IgA glomerulonephritis which are recognized increasingly in COL4A3-, COL4A4 - and COL4A5-associated disease." (PMID 35602506, 2022). "However, some variants in the COL4A3, COL4A4, or COL4A5 gene seem to increase the susceptibility to IgA nephropathy, which is supported by IgA deposits occasionally observed in the AS patients and the COL4A3, COL4A4, or COL4A5 gene variants reported in a minority of IgA nephropathy patients." (PMID 36699462, 2022).
prostate carcinoma (5 papers, 2009 to 2023). A carcinoma that arises from epithelial cells of the prostate gland. "Collagen genes were also reported to be regulated by Se-methylselenocysteine in a prostate cancer cell line (LNCaP), but only one of these (Col4a5) was regulated in the same direction in the present study." (PMID 21226930, 2011). "This would be consistent with the notion that methylation of JMJD2D could promote prostate cancer development through upregulation of CBLC and METTL27 as well as through downregulation of COL4A5, GLIS3, NPR1, OSR2, PLAGL1 and RSPO3." (PMID 38045004, 2023).
Renal cyst (5 papers, 2018 to 2026). A fluid filled sac in the kidney. "While the primary focus was on identifying COL4A1 variations, the study also included one patient with TBM disease and bilateral renal cysts who was heterozygous for a likely pathogenic missense variant in COL4A5." (PMID 40565535, 2025). "While ADPKD is predominantly associated with PKD1 and PKD2 gene variants, there are documented cases where individuals with pathogenic variants in COL4A3, COL4A4, or COL4A5 also present with renal cysts and even a clinical diagnosis of polycystic kidney disease (PKD)." (PMID 40565535, 2025). "Furthermore, the available evidence indicates that renal cysts can indeed be a feature in individuals harboring variants in COL4A3, COL4A4, and COL4A5." (PMID 40565535, 2025). "The presence of bilateral renal cysts in our patient is interesting, as, to the best of our knowledge, an association between COL4A5 variants and renal cysts has not been reported before." (PMID 30002862, 2018).
X-linked disease (4 papers, 2014 to 2025). X-linked form of disease. "ASDL is an X-linked inherited disorder resulting from mutations in the COL4A5 gene where myoma lesions are widely spread over the esophagus, trachea, bronchi, and genitalia." (PMID 36176479, 2022). "In family 3, in which we detected a COL4A5 donor splice site mutation (c.687 + 1G > A) known to cause XLAS, the disease was unusually severe (for X-linked disease) in the female patients I-2, II-2 and II-5 and unusually mild in the male patient III-2." (PMID 25381091, 2014).
breast carcinoma (3 papers, 2021 to 2023). "Our study also revealed that primary breast tumors stimulated increases in Col4A5 in premetastatic lungs and breast cancer-conditioned lung fibroblasts, which was consistent in our cell culture and animal studies." (PMID 37903851, 2023). "Knockdown of COL4A5 significantly suppressed the growth of luminal-type breast cancer cells." (PMID 38023248, 2023). "We also observed increased levels of Col4A5 and glypican (GPC) GPC1 in lung fibroblasts exposed to conditioned media from both breast cancer cells, which approached statistical significance." (PMID 37903851, 2023).
diabetic nephropathy (3 papers, 2020 to 2025). "In diabetic nephropathy, where COL-IV is a major deposited collagen, Smad3 binds to promoter regions of COL4A1A2, COL4A3A4, and COL4A5, a process inhibited by C-peptide." (PMID 40646747, 2025).
Kidney Cyst (3 papers, 2022 to 2025). Abnormal fluid filled sac within the kidney, either acquired or congenital. "A cystic phenotype is increasingly recognized in association with disorders caused by pathogenic variants in the COL4A3, COL4A4, and COL4A5 genes; several studies have investigated the prevalence of kidney cysts in individuals with these genetic variants." (PMID 40565535, 2025). "One explanation for the association of COL4A3, COL4A44, and COL4A5 variants with kidney cysts is that the cysts result from the distension of basement membranes weakened by disruption of the collagen IV α3α4α5 network." (PMID 40565535, 2025). "Single pathogenic variants in the collagen genes COL4A (COL4A5 in females) can result in mild COL4A-related disease phenotypes, where kidney cysts can be present." (PMID 40565535, 2025).
polycystic kidney disease (3 papers, 2020 to 2026). A usually autosomal dominant and less frequently autosomal recessive genetic disorder characterized by the presence of numerous cysts in the kidneys leading to end-stage renal failure. "In a recently report of a family with polycystic kidney disease, the c.2858G>T(p.(G953V)) variant in COL4A5 gene was identified in four individuals who had no clinical features of AS, which supported our findings." (PMID 31576025, 2020). "Interestingly, polycystic kidney disease (PKD) has been previously reported in few unrelated patients with COL4A4 and COL4A5 variants, occasionally even in the absence of other AS typical features." (PMID 38790225, 2024).
renal fibrosis (3 papers, 2021 to 2025). A final common manifestation of a wide variety of chronic kidney diseases characterized by glomerulosclerosis and tubulointerstitial fibrosis. "Our study suggested that an HA/CD44/TGFβ axis triggered by HAS2 overproduction due to COL4A5 deficiency could be strongly implicated in XLAS renal fibrosis." (PMID 40075271, 2025). "To investigate the mechanism underlying renal fibrosis, we used RNA-seq data described previously to screen differentially regulated genes involved in fibrosis in kidney tissues between hemizygous Col4a5-mutant male mice (XLAS) and healthy control males (HC)." (PMID 40075271, 2025). "The novel contribution of our study is finding that COL4A5 deficiency may lead to HAS2 overexpression and HA accumulation to activate CD44-TGFβ signaling, thereby promoting fibrosis, possibly suggesting that HAS2 and CD44 are potential therapeutic targets for impeding renal fibrosis in XLAS." (PMID 40075271, 2025). "Renal fibrosis, a final common pathway of CKD, was significantly reduced in the kidneys of losartan- or metformin-treated Col4a5 G5X Alport syndrome mice compared with control (MT)." (PMID 33782421, 2021).
autosomal dominant polycystic kidney disease (2 papers, 2022 to 2025). Autosomal dominant form of polycystic kidney disease. "The first genetic breakthroughs in nephrology were the mapping of autosomal dominant polycystic kidney disease (ADPKD) in 1985 and the identification of a mutation in COL4A5 causing Alport syndrome in 1990." (PMID 35881244, 2022).
Benign familial hematuria (2 papers, 2019 to 2022). "COL4A5 mutations are associated with the major X-linked form of the disease, and COL4A3 and COL4A4 mutations are associated with autosomal recessive, dominant forms, and benign familial hematuria." (PMID 30293132, 2019).
collagenopathies (2 papers, 2024 to 2025). "Seven families (5.7%) harbored disease-causing variants linked to collagenopathies (2 of the 4 cases with COL4A5 variants were females and 3 families with monoallelic COL4A3 genes)." (PMID 40677324, 2025). "Genetic findings that modified the diagnosis in 19 patients included mutations in patients with NPHP (NPHP1 [n = 4], TTC21B [n = 3], ANKS6 [n = 1], NPHP3 [n = 1], NPHP4 [n = 1]), collagenopathies (COL4A5 [n = 7], COL4A3 [n = 1]), and Fabry disease (GLA [n = 1])." (PMID 39363361, 2024).
colon cancer (2 papers, 2022 to 2023). "In vitro studies demonstrated that the expression of COL4A5/COL4A6 genes was down-regulated in colon cancer cell lines, suggesting that normal basement membranes were disrupted in progressive tumors, accompanied by a down-regulation of gene expression." (PMID 36674696, 2023).
glioblastoma (2 papers, 2021 to 2025). The most malignant astrocytic tumor (WHO grade IV).
glomerular nephritis (2 papers, 2020 to 2023). "X‐linked Alport syndrome (XLAS) is a progressive, hereditary glomerular nephritis of variable severity caused by pathogenic COL4A5 variants." (PMID 32543079, 2020).
glomerulosclerosis (2 papers, 2024 to 2025). A hardening of the kidney glomerulus caused by scarring of the blood vessels. "These insights align with our observation that glomerulosclerosis could be suppressed when COL4A5 expression was restored before a critical threshold, reinforcing the concept of a therapeutic window for intervention." (PMID 41290692, 2025).
Hypertension (2 papers, 2018 to 2026). The presence of chronic increased pressure in the systemic arterial system. "Salmons seem to be a good food resource for people to treat hypertension or improve health, and collagen subunit proteins col4a5 and col8a1 are potent antihypertensive agent substitutes for existence of numerous ATHPs in their sequences." (PMID 30279337, 2018).
ovarian carcinoma (2 papers, 2021 to 2023). A malignant neoplasm originating from the surface ovarian epithelium. "A total of 10 overlapped genes (SLC7A7, SLC7A8, COL4A5, etc.)and one metabolite (L-threonine) were significantly correlated with the pathway of protein digestion and absorption in ovarian cancer." (PMID 34539736, 2021).
renal dysfunction (2 papers, 2019 to 2025). "Pathogenic variants in the COL4A3, COL4A4, or COL4A5 genes disrupt the proper assembly and structure of collagen type IV, leading to impaired GBM integrity and progressive renal dysfunction, and may also affect ocular and cochlear structures." (PMID 40852417, 2025).
acute myeloid leukemia (1 paper, 2024). Acute myeloid leukemia (AML) is a group of neoplasms arising from precursor cells committed to the myeloid cell-line differentiation. "In a study of patients with acute myeloid leukemia, potential interaction network was identified involving long noncoding RNAs (lncRNA) UCA1/hsa-miR-16-5p/COL4A5." (PMID 39049724, 2024).
adenoma (1 paper, 2025). A neoplasm arising from the epithelium. "Among the identified molecular targets, ARRB1 was validated using RT-qPCR for adenoma, COL4A5 and RPS3A for CIS, and COL1A2 and MED10 for adenocarcinoma." (PMID 40362431, 2025). "RSP3A and COL4A5 were significantly overexpressed in CIS compared to adenoma and adenocarcinoma, respectively (p-value < 0.05)." (PMID 40362431, 2025). "In adenoma, ARRB1, CTBP1 and CTBP2 were overexpressed, suggesting their involvement in early tumorigenesis, whereas in CIS, RPS3A and COL4A5 were overexpressed, suggesting their involvement in the transition from benign to malignant stage." (PMID 40362431, 2025).
Aortic dissection (1 paper, 2025). Aortic dissection refers to a tear in the intimal layer of the aorta causing a separation between the intima and the medial layers of the aorta. "Microarray data from the Sandmann group identified downregulation of COL4A2 and COL4A5 in aortic dissection." (PMID 41497804, 2025).
Atrophy (1 paper, 2023). Any weakening or degeneration, especially through lack of use. "The ACTN4 mutation caused distinct electron-dense aggregates in podocyte cell bodies, while the COL4A5 mutation led to segmental sclerosis of glomeruli with marked interstitial fibrosis and tubular atrophy." (PMID 38139322, 2023).
cyst (1 paper, 2025). A sac-like closed membranous structure that may be empty or contain fluid or amorphous material. "According to this study, it is hypothesized that pathogenic variants in COL4A3/COL4A5 that disrupt the type IV collagen α3α4α5 network may result in weakened basement membranes in the distal tubule, making them more susceptible to cyst formation." (PMID 40565535, 2025).
dilated cardiomyopathy (1 paper, 2016). Cardiomyopathy which is characterized by dilation and contractile dysfunction of the left and right ventricles. "Upregulated COL4A5, COL9A1, COL21A1, and COL23A1 genes, encode collagens that have not previously been reported to be related to dilated cardiomyopathy." (PMID 27936202, 2016).
familial nephropathy (1 paper, 2025). "Among the 7 patients with a VUS+ in COL4A5 and COL4A4, 6 reported a first-degree familial nephropathy, 6 had reached end-stage kidney disease." (PMID 40630292, 2025).
fibrosis (1 paper, 2021). the formation of excess fibrous connective tissue in an organ or tissue in a reparative or reactive process. "Col4a5, Col6a6, and Fn1 genes in charge of producing collagen of ECM components and markers of iWAT fibrosis, were discovered to be uniquely decreased in cold." (PMID 34017267, 2021).
gastric cancer (1 paper, 2022). A primary or metastatic malignant neoplasm involving the stomach. "Peng reported that COL4A5 was involved in the initiation and progression of gastric cancer, and it could forecast the recurrence of the cancer." (PMID 36186476, 2022).
Krebs 2 carcinoma (1 paper, 2022). "The obtained data confirmed the strong overexpression of Mreg, Prg4, Col3a1, Selp, Marco, and Fgfr1 genes in Krebs-2 carcinoma, as well as Cdh11, Col4a5, Vcam1, Megf6, Scarf2, Scart1, and Cd14 genes in HH47." (PMID 36555446, 2022).
leiomyomatosis (1 paper, 2016). A condition characterized by the presence of numerous small benign smooth muscle neoplasms located throughout the body. "Unlike XLAS, which is related to the loss of the α5 (IV) chains due to mutations in COL4A5, leiomyomatosis is considered to be caused by the upregulation of the IRS4 gene, which is located next to COL4A528." (PMID 27377778, 2016).
liver cancer (1 paper, 2023). An epithelial or non-epithelial malignant neoplasm that arises from the liver. "TOP2A, CENPF, ACSL4, SPARC, and COL4A5 were significantly upregulated in patients with liver cancer, while they were downregulated by CTD treatment in HCC cells." (PMID 38017425, 2023).
posterior polymorphous corneal dystrophy (1 paper, 2014). Posterior polymorphous corneal dystrophy (PPCD) is a rare mild subtype of posterior corneal dystrophy characterized by small aggregates of apparent vesicles bordered by a gray haze at the level of Descemet membrane, generally with no effect on vision. "Neither sensorineural hearing loss nor typical COL4A5-related ocular abnormalities (dot-and-fleck retinopathy, anterior lenticonus, and the rare posterior polymorphous corneal dystrophy) were present in patients of this family." (PMID 25110662, 2014).
prostate tumors (1 paper, 2023). "On the other hand, we focused on six genes (COL4A5, GLIS3, NPR1, OSR2, PLAGL1 and RSPO3) that were significantly downregulated in human prostate tumors as well as upregulated in DU145-R427 cells, suggesting that these genes might negatively interfere with prostate tumorigenesis." (PMID 38045004, 2023).